ZEB2 (zinc finger E-box binding homeobox 2)
Diseases named in the same sentence as ZEB2 in open-access papers (continued):
Sharing a sentence is not in itself a finding about the gene and the disease.
cancer (continued). "This decrease in apoptosis by ZEB2 induction is of importance in chemotherapy, since cancer cells can attain chemoresistance via reducing their sensitivity into chemotherapy-mediated apoptosis." (PMID 32664703, 2020). "Knockdown of hsa-circ-0004771 sensitizes cancer cells to apoptosis and inhibits their progression through miR-653 up-regulation and subsequent inhibition of ZEB2." (PMID 32664703, 2020). "These genes encode for proteins with well-known roles in cancer progression and normal stem cell maintenance (KIT), angiogenesis (SERPINE), and epithelial-mesenchymal transition (TWIST1, TWIST2, and ZEB2)." (PMID 31013771, 2019). "ZEB1 and ZEB2 are key modulators of cancer-initiating cell properties in HNSCC, EMT process, metastasis and cisplatin resistance." (PMID 30755200, 2019). "We observed novel recurring amino acid changes in the cancer-related genes ZEB2 H1038R (n = 3) and PTPN11 S502L (n = 2)." (PMID 30862934, 2019). "It is widely accepted that ZEB2 was involved in cancer cell invasion, mainly through induction of EMT18,41–43." (PMID 30783098, 2019). "Amongst the candidates, ZEB2, an oncogene gene that plays an important role in various cancers, was predicted to be an miR-101 target and was selected for further experimental verification." (PMID 30692230, 2019). "The results described in this work, open the possibility to epigenetically inhibit ZEB2 expression by targeting BET proteins in cancer cells." (PMID 31758045, 2019). "This study demonstrates previously unrecognized novel roles of ZEB2 protein in cancer cell survival and angiogenesis beyond invasion during cancer progression." (PMID 29416649, 2018). "It is intriguing that ZEB2 positively links cancer cell invasion with cell cycle progression and cell survival, given that cell proliferation and migration are mutually exclusive processes." (PMID 29416649, 2018). "We suggest that this constitutive repression of Zeb2 leads to plastic EMT in the cancer cells dictated by inflammation and Tgf-β1 accumulation concentrated around airways." (PMID 29930325, 2018). "ZEB2 nuclear localization has been identified in several cancer types, and its overexpression is correlated with the malignant progression." (PMID 30445998, 2018). "Flow cytometric analysis also showed that ZEB2 suppression resulted in a moderate increase in apoptosis induction, indicating that ZEB2 is able to confer anoikis resistance to cancer cells in vitro." (PMID 29416649, 2018). "We have been investigating the roles of ZEB2 in the induction of mesenchymal genes during cancer cell invasion and metastasis." (PMID 29416649, 2018). "Previously, we showed that ZEB2 cooperates with the transcription factor Sp1 to function as a transcriptional activator of vimentin, integrin α5, and cadherin-11, which promotes cancer cell invasion." (PMID 29416649, 2018). "Kahlert et al11 previously reported cytoplasmic expression of ZEB2 at the invasive front of primary CRCs identified as having poor cancer-specific survival." (PMID 30646224, 2018). "Our study suggests that cancer cells accelerate the aggressiveness of a malignancy by themselves via cooperation between ZEB2 and Sp1 and subsequent acquirement of a proliferative and viable phenotype." (PMID 29416649, 2018). "Based on our findings in cell culture, we suggest that ongoing repression of Zeb2 in the cancer cells allows the cells to respond to Tgf-β1 concentrated around airways and induce Zeb1 and EMT to facilitate invasion." (PMID 29930325, 2018). "ZEB1 and ZEB2 have overlapping roles in cancer metastasis but there is evidence that they also have separate, non-redundant roles in development and cancer." (PMID 29963231, 2018). "Expanding and differential roles of ZEB1 and ZEB2 have been identified in various types of cancers in recent years." (PMID 28618162, 2017). "The mammalian homologs of Zfh1 known as ZEB1 and ZEB2 have been largely studied for their role in cancer progression." (PMID 29072161, 2017).
cancer (continued). "Epithelial-mesenchymal transition (EMT) is regulated by various transcription factors, including Twist, Snail, Slug, ZEB1, and ZEB2, and are deregulated in many cancers." (PMID 28423495, 2017). "For examples, oncogenic KRAS regulated miR-200c, while miR-200c targeted ZEB1/ZEB2 (ZEB1/ZEB2 functions as an oncogene to promote the cancer metastasis)." (PMID 28736730, 2017). "Although ZEB1 protein is present in the majority of carcinoma cell lines exhibiting mesenchymal properties, expression of ZEB2 is uncommon." (PMID 28783176, 2017). "The miR-200 family, which consists of miR-200a, miR-200b, miR-200c, miR-141, and miR-429, is known for its capability to regulate epithelial-mesenchymal transition (EMT) program in cancer cells via the posttranscriptional repression of ZEB1 or ZEB2." (PMID 26934322, 2016). "We found that FLO-1 expressed significantly higher mRNA levels of the mesenchymal markers SNAI1, ZEB1 and ZEB2 compared to the other cancer cell lines." (PMID 27863424, 2016). "The transcriptional repressor zinc-finger E-box binding homeobox 1 and 2 (ZEB1 and ZEB2) are crucial inducers of EMT in various cancers and have been shown to promote invasion and metastasis of cancer cells." (PMID 27240340, 2016). "ZEB2NAT depletion reversed CAF-CM-induced EMT and invasion of cancer cells, as well as reduced the ZEB2 protein level." (PMID 26152796, 2015). "The study of ZEB2 expression regulation is of pivotal importance to understand the cancer progression." (PMID 26136338, 2015). "In this context, our study of the mesenchymal factor ZEB2 expression, function and regulation aimed to provide new elements for a deeper knowledge of cancer dissemination and a more effective therapeutic approach." (PMID 26136338, 2015). "Zeb2, as a transcription factors, has been detected in many cancers, and it is well-known to repress E-cadherin transcription via directly binding to the E-boxes within the E-cadherin promoter." (PMID 25871475, 2015). "In relevance to these data, it has been reported that ZEB2 expression is higher in various cancers compared with normal tissues." (PMID 25762639, 2015). "Since it is well recognized that EMT is involved in cell migratory capacity in different carcinomas, we explored the role of ZEB2 in this specific context." (PMID 26136338, 2015). "In these subnetworks, different RNAs are located on PCSRs including GAPDH, ZEB2, mir-20b, mir-21, mir-141 and mir-200c supporting the important effects of these RNAs and their regions in cancer." (PMID 24796549, 2014). "Among the predicted candidates, ZEB2 was of interest in this study, considering the crucial roles of ZEB2 in the development of human cancers." (PMID 24626466, 2014). "It is reported that ZEB2 is a vital EMT inducer through suppressing E-cadherin or inducing vimentin expression in human cancer." (PMID 24626466, 2014). "The loss of E-cadherin expression results in EMT and cancer metastasis, and E-cadherin has been shown to be inhibited by several EMT regulators, including SNAIL, TWIST, ZEB1, and ZEB2." (PMID 25431208, 2014). "Network analysis indicates that DDX5, LIFR, ZEB2, mir-21, mir-27b, mir-30a, mir-141, mir-182 and mir-200c were shared across different constructed networks, indicting their crucial role in cancer biology and progression, which has been reported previously." (PMID 24796549, 2014). "In contrast, DCN (chr12q21.33), LIFR (chr5p13.1), ABCA8 (chr17q24.2), C7 (chr5p13.1) and ZEB2 (chr2q22.3) on predicted PCSRs were down-expressed in 9, 7, 8, 8 and 8 cancers, respectively." (PMID 24796549, 2014). "The miR200 by inhibiting the ZEB1 and ZEB2 proteins production induce the mesenchymal-to-epithelial transition in cancer cell lines and reduce their aggressiveness." (PMID 24933019, 2014). "With regards to the role of ZEB2 in different human cancer types, some of the reports are totally contradictory." (PMID 23658743, 2013).
cancer (continued). "Another key family of factors that regulate EMT in NC and cancer cells is the Zeb family of transcription factors, containing Zeb1 and Zeb2." (PMID 23576382, 2013). "In previous studies, miR-200a regulating the EMT process by targeting EMT-activating transcriptional factors ZEB1 and ZEB2 has been thoroughly elaborated in different types of cancers." (PMID 24260215, 2013). "The relevance of the ZEB2 protein to cancer progression has been investigated in various human tumors." (PMID 23658743, 2013). "The miR-200 family and miR-205 regulate EMT by targeting ZEB1 and ZEB2, which function as transcriptional repressors of E-cadherin expression, thereby reducing the aggressiveness of cancer cells." (PMID 23554909, 2013). "With regards to the role of ZEB2 in the progression of human cancers, some of the results are totally contradictory." (PMID 22393452, 2012). "It has been suggested that overexpression of ZEB2 plays a putative role in oncogenic transformation since it was identified in a large-scale screen for cancer related genes." (PMID 21303533, 2011). "Epithelial Mesenchymal Transition (EMT) was another pathway depleted upon knockout, and subsequent analysis revealed a significant correlation between NNMT and EMT-related genes (VIM, CDH2, FN1, TGFB1, and ZEB2) in both the Cancer Cell Line Encyclopedia (CCLE) panel and patient data." (PMID 41997904, 2026). "Furthermore, the inflammatory cancer cell subtype identified here expressed high levels of the EMT transcription factor Zeb2, particularly in Mir34aΔMye CACs." (PMID 39425000, 2025). "Notably, Snai1 upregulates the expression of Zeb family proteins in carcinoma cells by inducing the expression of a natural antisense transcript for ZEB2 (NAT)." (PMID 40134588, 2025). "In 2001, E12/E47 basic helix-loop-helix transcription factor (also called TCF3) was shown to evoke an EMT effect in MDCK kidney cells, and the ZEB family transcription factors, ZEB1 and ZEB2, were reported to induce an invasive phenotype in cancer cells, linking their function in regulating EMT." (PMID 39164745, 2024). "On the other hand, it is uncertain if ZEB2 regulates PD‐L1 expression in cancer." (PMID 39362647, 2024). "Therefore, both ZEB1 and ZEB2 proteins are inducers of cancer metastasis, and notably, their expression level is controlled by circRNAs in cancer." (PMID 38733529, 2024). "Besides its role in regulating the EMT, the overexpression of ZEB2 in cancer cells results in the deregulation of the cell cycle, inhibition of apoptosis, increased cell proliferation and cancer progression." (PMID 38473317, 2024). "In many cancers, the loss of E-cadherin is attributed to transcription factors such as SNAIL, SLUG, TWIST, ZEB1, and ZEB2, which bind to E-box sequences in the promoter region of the CDH1 gene and negatively regulate its expression, often through promoter methylation." (PMID 39728992, 2024). "Even though ZEB2 is predominantly perceived as a transcriptional repressor, a number of reports have also identified its role as a transcriptional activator, mostly in the context of cancer." (PMID 38719798, 2024). "Since TGF‐β promotes anchorage‐independent growth of cancer cells, it remains unclear why ZEB2 promotes proliferation in soft agar to a greater extent than ZEB1." (PMID 39362647, 2024). "Several transcription factors (TFs) mediate the development of EMT, including SNAIL1/SNAIL2, TWIST1/TWIST2 and ZEB1/ZEB2, which are overexpressed in various carcinomas along with the under expression of the metastasis suppressor Raf Kinase Inhibitor Protein (RKIP)." (PMID 39335152, 2024). "ZEB1 and ZEB2 overexpression has been found in several human cancers, including NSCLC." (PMID 36376711, 2023). "The ZEB2 gene is a one of the regulators of the EMT process that induces invasion of cancer cells." (PMID 36109686, 2023). "The use of cancer cell lines of a genomica unstable nature may create possible bias in ChIP-seq, and in any case, they overproduce ZEB2." (PMID 36980900, 2023).
cancer (continued). "Among these, ZEB2 has been shown to characterize the transcriptional landscape of quiescent cancer cells (QCCs) in colorectal and lung cancer, thus substantiating its key role in the regulation of cancer cell quiescence." (PMID 36757577, 2023). "Several non-coding RNAs were found to target ZEB1 and ZEB2 translation in various cancer types." (PMID 37927751, 2023). "In addition, MALAT1 has been shown to post-transcriptionally upregulate ZEB2 in cancer, and ZEB2 was the third most upregulated gene in AML-X." (PMID 37528411, 2023). "ZEB2 is a transcription factor that mainly promotes epithelial-to-mesenchymal transition and regulating differentiation, cancer stem cell-like traits, apoptosis, cell cycle arrest, and metastasis of cancers." (PMID 36762036, 2023). "ZEB1 and ZEB2 can induce EMT leading to cancer cell migration, invasion, and metastasis." (PMID 37770496, 2023). "Thus, we performed a comprehensive meta-analysis to evaluate the prognostic value of ZEB2 in different types of cancer, including OV." (PMID 35723302, 2022). "However, direct linking is quite likely because data on direct interactions of miR-203 with ZEB1 and ZEB2 in other cancer types were obtained, as cited above." (PMID 35163224, 2022). "As ZEB2 was previously implicated in quiescence/chemoresistance in CRC, its involvement also in NSCLC QCCs suggests a broad role of this factor in regulating cancer quiescence." (PMID 36077264, 2022). "Additionally, RING1B has also been shown to promote EMT and metastatic progression of cancer cells by activating the expression of ZEB2 and inhibiting the expression of E-cadherin, further demonstrating its important role in cancer development." (PMID 36076977, 2022). "ZEB2 overexpression is known to have an aggressive correlation in a variety of cancers that may be involved in malignant transformation." (PMID 35723302, 2022). "Studies have shown that Wnt/β-catenin signaling could upregulate the expression of Slug (Snai2), ZEB1, and ZEB2 in cancer cells, thereby reducing the level of E-cadherin to promote cell migration." (PMID 36398031, 2022). "In addition, the detailed mechanisms by which ZEB2 contributes to the correlation in cancer should be elucidated further." (PMID 35723302, 2022). "Herein, we identified a correlation between ZEB1 and ZEB2 in various cancers." (PMID 35723302, 2022). "Furthermore, CM-PM increased the expression of the mesenchymal markers Slug, Zeb1, and Zeb2 and reduced the expression of the epithelial marker E-cadherin in cancer cells at both the transcriptional and translational levels." (PMID 36352257, 2022). "R software was used to study the expression of ZEB2 in 33 types of cancer." (PMID 36072677, 2022). "The detailed mechanisms of ZEB1 and ZEB2 in cancer should be elucidated." (PMID 35723302, 2022). "ZEB1 and ZEB2 may have multiple functions that will be elucidated by analyses of specific cancer types in the future." (PMID 35723302, 2022). "Tumorigenicity and invasiveness are important acquired characteristics for the development and progression of cancer, and could be regulated by transcription factors associated with EMT, such as ZEB1, ZEB2, SNAI1, SLUG, and STAT3." (PMID 35723302, 2022). "Interestingly, these findings revealed that ZEB1 and ZEB2 were positively correlated in all cancer types." (PMID 35723302, 2022). "Thus, we performed a meta-analysis to evaluate the prognostic biomarker value of ZEB2, which is involved in the progression and development of various types of cancer, including OV." (PMID 35723302, 2022). "MTBP could promote human cancer cells’ proliferation or metastasis by functioning as a co-activator of c-MYC (cellular-myelocytomatosis viral oncogene) or ZEB2 (Zinc Finger E-Box Binding Homeobox 2)." (PMID 34249768, 2021).
cancer (continued). "These marginal significances may be explained by the biological interactions of the EMT cascade: both Snail and Zeb2 are well-ascertained effectors of the EMT process in many cancer types, acting as nuclear factors downstream of the Wnt/ß-catenin pathway." (PMID 34283055, 2021). "Hence, targeting the circRNA/miR/ZEB2 axis can pave the way into effective inhibition of proliferation and migration of cancer cells." (PMID 32664703, 2020). "Consequently, the cancer cells from metastasis exhibited a significantly enhanced expression of mesenchymal marker vimentin, twist and zeb2 and a decrease of epithelial marker E-cadherin." (PMID 32225005, 2020). "Evidently, ZEB2 induction dually enhances proliferation and metastasis of cancer cells." (PMID 32664703, 2020). "Particularly, lncRNAs can affect upstream transcription factors of ZEB2 in cancer metastasis." (PMID 32664703, 2020). "It is also vital to explore the relevance of ZEB1 and ZEB2 proteins in cancer therapy." (PMID 32664703, 2020). "As such, targeting miR/ZEB2 axis may be a promising strategy in cancer therapy, as it increases the sensitivity of cancer cells toward chemotherapy." (PMID 32664703, 2020). "These miRNAs exhibit tumor suppressor activity to antagonize EMT associated with cancer metastasis by silencing E-cadherin, such as ZEB1 and ZEB2 in various cancers such as colorectal cancer, gastric cancer, pancreatic cancer, ovarian cancer, and nasopharyngeal cancer." (PMID 33007962, 2020). "Moreover, Orai1 is capable of endowing non-tumorigenic immortalized oral epithelial cells with self-renovation, and concurrently enhances transcribing pluripotent and cancer stem cells-associated agents such as Nanog, Sox2, KLF4, Oct4, Zeb1, Bmi1, and Zeb2." (PMID 32280305, 2020). "Thus, to further elucidate the physiological relevance of FBXW7/ZEB2 interaction, we used organoids (mini-gut), which are being used to model diseases including cancer." (PMID 30783098, 2019). "Thus, expression of SBSN in low‐adherent cells can be responsible both for EMT due to increased expression of Snail and Zeb2, and for induction of cancer stemness." (PMID 30919591, 2019). "Similarly, lncRNAs ZEB1 antisense 1 (ZEB1-AS1) and ZEB2 natural antisense transcript (ZEB2-NAT) promote the expression of ZEB1 and ZEB2, respectively, leading to increased metastasis and poor prognosis in numerous types of cancer." (PMID 30791369, 2019). "Moreover, decreased expressions of mesenchymal transcription factors Zeb1 and Zeb2 were observed in cancer cells treated with MBCD as compared to untreated cells." (PMID 30625181, 2019). "Therefore, the EMT process that is associated with the expression of E-cadherin, vimentin, ZEB1 and ZEB2 is generally used to indicate the ability of cancer cell metastasis and invasion." (PMID 29559853, 2018). "In particular, we aimed to determine whether cooperation between ZEB2 and Sp1 promotes cancer cell survival and paracrine activation of endothelial cells." (PMID 29416649, 2018). "However, the level of Zeb1 was still sufficient to maintain repression of Zeb2, allowing the cancer cells to respond to Tgf-β1 accumulating at sites of inflammation and airway invasion to re-establish Zeb1hi and EMT in the invading cells." (PMID 29930325, 2018). "ZEB2 has been confirmed as miR-145 target gene in cancer cells." (PMID 29375381, 2017). "Thus, the detailed mechanisms by which ZEB1 and ZEB2 contribute to poor prognosis in cancer remain to be elucidated." (PMID 28618162, 2017). "Interestingly, so far functional interaction between miR-200 and Zeb2 has been exclusively reported in cancer or cultured stem cells." (PMID 27767083, 2016). "Previous studies showed that MALAT-1 promotes cancer progression, mainly through the regulation of gene expression, for example, the epithelial mesenchymal transition associated genes, ZEB1, ZEB2, and Slug and the apoptosis related genes, CASP3, CASP8, BAX, BCL2, and BCL2L1." (PMID 26989678, 2016).